CRP (C-reactive protein)
Diseases named in the same sentence as CRP in open-access papers (continued):
Sharing a sentence is not in itself a finding about the gene and the disease.
Hypertension (continued). "ACM was best predicted by a combination of d‐dimer, CRP, LDH, NT pro‐BNP, age, moderate/severe TR, and arterial hypertension (AUC = 0.83, 95% CI 0.78–0.88)." (PMID 35789499, 2022). "Regarding the composite outcome death/intubation, the variables selected for the multivariate analysis were age, clinical status at the beginning of follow-up, hypertension, smoke, use of ACE-I, PaO2/FiO2, respiratory rate and CRP." (PMID 35081151, 2022). "Hypertension, the use of angiotensin-converting enzyme inhibitors (ACE-I) at home, PaO2/FiO2, respiratory rate and C-reactive protein (CRP) were selected for the multivariate analysis." (PMID 35081151, 2022). "In the FAR-H group, the fibrinogen, FPG, HbA1C, BNP, CRP, and WBC levels, the proportion of IMD, and occurrence of atrial fibrillation, hypertension, and the use of SGLT2i were significantly higher, compared to the FAR-L group." (PMID 36371183, 2022). "A model including CRP, LDH, troponin I, age, and arterial hypertension reached an AUC = 0.86, 95% CI 0.82–0.90, when predicting mechanical ventilation." (PMID 35789499, 2022). "Models were adjusted for age, sex, hypertension status, smoking status, HDL-c, total cholesterol, CRP and eGFR." (PMID 34562103, 2022). "This study showed that the proportion of hypertension patients in the atherosclerosis group was higher, and the items of LDL-C, CRP, and CIMT in the atherosclerosis group were also higher than those in control group (P < 0.05)." (PMID 35538435, 2022). "In women the differences are due to: smoking (at the bifurcation), hypertension (in the common carotid artery), total and LDL cholesterol (at the bifurcation and in the internal carotid artery), and hs-CRP (in the common and internal carotid arteries)." (PMID 35994446, 2022). "In the HD group, COPD, hypertension, malignant tumor, BUN, and CRP were extracted in a univariate analysis." (PMID 35999867, 2022). "Eleven factors were used, including SBP, DBP, HDL, LDL, total cholesterol, triglycerides, waist to hip ratio, blood glucose, CRP, DHAS, and a history of medication controlling metabolic diseases and hypertension." (PMID 35804816, 2022). "After further adjustment for education level, BMI, hypertension, FBG, and CRP, as well as the use of clozapine, olanzapine, risperidone and quetiapine, higher levels of NHDL-C, and ApoB were still associated with lower odds of cognitive impairment." (PMID 36506447, 2022). "Little is known about pathology, the role of CRP in type 1 diabetes, CAD, hypertension and cardiovascular diabetes." (PMID 35178206, 2022). "High-sensitivity C-reactive protein (hs-CRP) and interleukin 6 (IL-6) were dramatically increased compared with periodontitis patients with NBP and with hypertension (P < 0.05)." (PMID 35813436, 2022). "We constructed 2 models: model 1, only adjusted for age; model 2, adjusted for age, sex, education, smoking status, alcohol consumption, physical activity, BMI, waist circumference, SBP, DBP, history of hypertension, TC, SUA, eGFR, and CRP." (PMID 35721750, 2022). "Overall, current smokers, current drinkers, obese workers, or those with high blood pressure, high TG, high total cholesterol (TC), high low-density lipoprotein cholesterol (LDL-C), high hs-CRP, and low HDL-C are more likely to have a decreased eGFR." (PMID 36142036, 2022). "Inflammatory mediators such as CRP, IL-1β,IL-6, TNF–α and reactive oxygen species have been proposed to contribute essential hypertension through several mechanism including enhancement of arterial stiffness, endothelial dysfunction." (PMID 37654837, 2022). "After adjusting for these factors, the significant variables were high blood pressure, low HDL-C, and high hs-CRP." (PMID 35873099, 2022). "In univariate analysis, significant difference was found in such baseline variables as GCS score at ICU admission (p< 0.001), CRP score at ICU admission (p< 0.001), sex (p< 0.001), hypertension (p= 0.039), and smoking status (p= 0.002) between SAP and non-SAP." (PMID 34925251, 2021).
Hypertension (continued). "Compared with patients without CA-AKI, those with CA-AKI had a higher prevalence of hypertension, type 2 diabetes, CKD, and heart failure, had lower eGFR, and were more likely to present with higher pre-procedural CRP levels." (PMID 34297744, 2021). "Five studies provided data on the CRP difference between HSD versus LSD and were included in the meta-analysis (n = 273, weighted age 47.7 ± 8.4 years, men 47%, hypertension 23.4%)." (PMID 34444792, 2021). "The risk nomogram incorporated several factors, including sex, age, SBP, CRP, ESR, TC, LDL, and the history of hypertension, AF, and CHD." (PMID 34081620, 2021). "This may be due to the difference in the study population; all the positive correlation studies between CRP levels and the risk of hypertension were conducted in the general population and did not examine the relationship with hypertensive status in a diabetic cohort." (PMID 34925916, 2021). "However, other studies did not observe an association between baseline CRP and the occurrence of hypertension, suggesting there may not be a significant association." (PMID 34925916, 2021). "Cross-sectional studies showed that acute phase reactants such as C-reactive protein (CRP) and cytokines (lL-6 and TNF-α) are related to components of the MS, such as BMI, WC, resistance to insulin, hypertension, and dyslipidemia." (PMID 34957175, 2021). "Presence of hypertension (p = 0.006), CKD (p < 0.001), lower hemoglobin (p = 0.034) and lower CRP (p = 0.004) at the hospital admission and nephrotoxin exposure (p < 0.001) were independent risk factors for the development of AKD." (PMID 34640618, 2021). "Previous study showed an association of baPWV and augmentation index with inflammatory markers, such as CRP, tumor necrosis factor-alpha (TNF-α) and Interleukin-6 (IL-6) in hypertension patients and CRP in healthy individuals." (PMID 34330221, 2021). "Patients had higher levels of C reactive protein (CRP), erythrocyte sedimentation rate and triglycerides and were more likely to have hypertension, while the controls were more likely to report a family history of CV events." (PMID 33547230, 2021). "Patients were comparable for age (p = 0.417), gender (p = 0.448), BMI (p = 0.079), prevalence of hypertension (p = 0.500), CVD (p = 0.407) and C-reactive protein (p = 0.404)." (PMID 33958634, 2021). "In this model, age, male gender, hypertension, COPD, dependency/frailty, creatinine levels, CRP > 60 U/L and LDH > 400 U/L were also independently associated with all-cause mortality." (PMID 33063540, 2021). "We found that 13 parameters had a p-value <0.05, namely, age, alkaline phosphatase, breathlessness, CRP, SGOT, cough, hypertension, comorbidities, respiratory rate, sodium, TLC count, total proteins, and urea." (PMID 35047415, 2021). "PWV was directly related to age, BMI, systolic blood pressure, estimated duration of hypertension, plasma levels of fasting glucose, LDL cholesterol, triglycerides, C-reactive protein, and Lp(a), and inversely related to HDL cholesterol." (PMID 34829739, 2021). "The total WMH burden was significantly higher among patients with older age, hypertension, prior stroke or TIA, history of anti-platelet or anti-hypertensive agent usage, lower eGFR levels, and higher SBP, hs-CRP, Hcy, TMAO, and choline levels." (PMID 33868152, 2021). "After K–M analysis, we found that age, hypertension, T2DM, N/L, CRP, AST, ALB, BUN and D-dimer had effects on patient outcomes." (PMID 32631365, 2020). "Compared with the control group, hypertension patients exhibited higher SBP, DBP, high-density lipoprotein cholesterol (HDL-C), creatinine (CREA), C-reactive protein (CRP), homocysteine (Hcy), and angiotensin II (Ang II)." (PMID 32626541, 2020). "The variables included in multiple regression were age and educational level (1st level); consumption of raw vegetables and whole cereals (2nd level); and hypertension, HOMA-IR, fasting insulinemia, hypertriglyceridemia, HDL, and CRP (3rd level)." (PMID 32498226, 2020).
Hypertension (continued). "These patients had a lower peak temperature and presented with higher lymphocyte counts but lower levels of AST, LDH, CRP, and APTT, and more comorbidities of hypertension or chronic diseases in the respiratory system compared with patients without RP." (PMID 33147282, 2020). "Age, CRP, HbA1c, FPG, LDL-C, BMI, TG, SBP, SUA, and DBP were significantly higher in hypertension than those in the normotension." (PMID 32293295, 2020). "Interestingly, reducing the risk of hypertension may be difficult as none of the considered lifestyle factors but only CRP, maternal BMI and familial predisposition were found to be influencing factors." (PMID 32943762, 2020). "Our univariate analysis identified age, hypertension, anti-CCP antibody positivity, rheumatoid factor positivity, a high ESR, high CRP levels, and dyslipidemia of LDL-c, TC, triglycerides and HDL-c as independent predictors of CHD." (PMID 32112552, 2020). "Significant interactions were tested in the multivariate model (age × CRP > 3 mg/L, troponin peak × STEMI, hypertension × chronic kidney disease, history of CAD × STEMI, sex × STEMI; sex × smoking), without changing the results of the model." (PMID 31810178, 2019). "Tx: transplantation, CRF: Chronic renal failure, HT: Hypertension, RA: Romatoid arthritis, CRP: C reactive protein." (PMID 30761877, 2019). "Serum resistin levels along with CRP and TLC are significantly raised in patients of hypertension and coronary artery disease while resistin levels revealed significantly positive correlation with TLC in hypertensive patients of myocardial infarction." (PMID 31258568, 2019). "Although the study subjects were overweight-to-obese and had hypertension or MetS, they were metabolically healthy (excluding T2DM), limiting a further reduction of parameters such as glucose, hs-CRP, and hs-TNFα which were already low at baseline." (PMID 31068933, 2019). "Numerous cardiovascular risk factors have been shown in patients with PHPT, including hypertension and elevated CIMT, insulin resistance, and CRP." (PMID 31385484, 2019). "In the present study, WEC significantly reduced the serum levels of CRP, TNF-α, IL-6, and sVCAM-1 in middle-aged and elderly subjects with overweight or prehypertension/mild hypertension." (PMID 31394768, 2019). "Compared with the volunteers who slept 6–8 h/day, those who slept <6 h/day with or without insomnia symptoms had significantly increased odds ratios of high blood pressure, high FBG, and high CRP in all models (p < 0.05), and low HDL-C in model 1 (p < 0.05)." (PMID 31404954, 2019). "The ERI showed a significant positiveassociation with serum ferritin and C-reactive protein, percentage interdialyticweight gain, and continuous usage of angiotensin receptor blocker (ARB)hypertension medication." (PMID 29742267, 2018). "By a logistic regression analysis, serum CRP levels >1.86 μg/mL have been found to predict MAO also considering maternal age, hypertension, and GDM." (PMID 30533423, 2018). "After adjusting for covariates such as age, gender, BMI, FBG, TNF-α, IL-6 and hs-CRP, GLM analyses showed that subjects with PWV and hypertension progression had higher baseline PWV, follow-up PWV and △PWV than those with no PWV and hypertension progression." (PMID 29433526, 2018). "The CMV IgG antibody titers were positively correlated with arterial BP, greater grade of hypertension and hypertensive TOD, and CRP and IL-6 levels." (PMID 28837559, 2017). "The participants with hypertension with TOD were more likely to be older (P<0.05) and had higher BP (including SBP, DBP, and MAP), CMV IgG antibody, CRP, IVSd and LVIDd values (P<0.05) than those with hypertension without TOD." (PMID 28837559, 2017). "Essential hypertension (EH) patients exhibited a marked increase in CMV IgG antibody, CRP, TNF-α, and IL-6 levels." (PMID 28837559, 2017).
Hypertension (continued). "Age together with other factors such as duration of hypertension, BMI, total cholesterol, LDL-c and C-reactive protein correlated with retinal changes in our patients." (PMID 28828178, 2016). "Significant positive correlations were observed between age, duration of hypertension, body mass index, total cholesterol, LDL-c and C-reactive protein with retinopathy." (PMID 28828178, 2016). "Hypertension, systolic blood pressure, HDL cholesterol, and CRP were also significantly higher among this group of men (p = <.0002.0012.0006.003, respectively)." (PMID 27301295, 2016). "By contrast, elevated levels of CRP, VEGF and IL-8 as representative of inflammation correlated with hypertension." (PMID 27166185, 2016). "As an inflammatory substance, C-reactive protein (CRP) is considered an important pathophysiological factor in the development and progression of hypertension." (PMID 26858795, 2016). "On Cox univariate analysis showed that hs-CRP (p = 0.002), NLR (p< 0.001), PLR (p = 0.07), eGFR (p < 0.001), LV ejection fraction (p < 0.001), hypertension (p = 0.003) and DM (p = 0.030) were significant predictors." (PMID 26207383, 2015). "However, in the multivariate model, non-carriers had higher CRP than mutation carriers and CRP could predict post-operative residual hypertension." (PMID 26066391, 2015). "In the present study, we showed that the plasma levels of CRP, IL-6 and TNF-α were significantly increased in acute TAAD patients (before T6) compared to those in uncontrolled hypertension and healthy volunteers." (PMID 25592634, 2015). "The presence of atherosclerotic plaques showed a positive correlation with age, hypertension, history of arrhythmia, IMT, Charlson comorbidity index, pulse pressure, left ventricular mass index, CRP and fibrinogen levels." (PMID 26029907, 2015). "In the current study, the average values of CRP, IL-6 and TNF-α in patients with chronic TAAD and hypertension tended to be higher than those in the healthy controls (Chronic TAAD vs. Healthy, P = 0.06; uHT vs. Healthy, P = 0.09)." (PMID 25592634, 2015). "We evaluated the association between mental well-being, assessed by GHQ-12, presence of hypertension, SUA and hs-CRP in our study population; along with other demographic information." (PMID 25237581, 2014). "A statistically significant difference was identified between the groups in hematocrit, platelet, creatinine, CRP, D-dimer, TAT, F1+2, and sEPCR levels and in hypertension (HT) and coronary arterial disease (CAD) rates." (PMID 25035668, 2014). "After adjusting their model for age, gender, hypertension, inflammation, CRP-lowering medication, and other covariates, PLMS >45 per hour remained a significant predictor of CRP (OR 8.60; 95 % CI 1.23–60.17; p < 0.03)." (PMID 23963470, 2014). "The AUC associated with the ROC analysis of model 1 (including age, sex, the BMI, smoking habit, the UACR, hypertension, dyslipidemia, duration of T2DM,as well as levels of CRP, uric acid, and HbA1c) was 0.81 (95% CI, 0.74–0.87)." (PMID 24655436, 2014). "In addition, a number of other exercise-related factors including age, smoking status, hypertension, and cholesterol levels may contribute to exercise-related inflammatory benefits as each have been shown to be inversely correlated with C-reactive protein (CRP) concentrations." (PMID 25178630, 2014). "HIV-infected subjects were of similar median age, and had similar rates of hypertension, total cholesterol, LDL, high sensitivity CRP (hsCRP), and current smoking rates compared to HIV-uninfected subjects." (PMID 24086545, 2013). "However, the precise relationship between CRP and hypertension remains unclear." (PMID 23978069, 2013). "Therefore, the rs7542235 (CFHR1–3Δ) may contribute to hypertension risk by increasing inflammatory response, and rs2274700 (A473A) is likely to be in LD with other genetic variants that affect expression of CFH or binding capacity of CFH with CRP." (PMID 22848687, 2012).
Hypertension (continued). "Notably, the associations of rs2274700 (A473A) with DBP (P = 2.1×10−3), SBP (P = 8×10−5) and hypertension risk (P = 7.9×10−3) were significant only in the individuals with low CRP levels (<2.0 mg/l), but not in those with CRP levels ≥2.0 mg/l (P≥0.0807) (P for interaction ≤0.0467)." (PMID 22848687, 2012). "C-reactive protein (CRP), leukocyte adhesion molecules, chemotactic and pro-inflammatory cytokines and heat shock proteins were found to be increased in patients with essential hypertension." (PMID 22474401, 2012). "She had been diagnosed with TA at the age of 4 years after presenting with hypertension and persistently raised inflammatory markers (ESR 50-105 mm/hour; CRP 40-95 mg/L)." (PMID 21288360, 2011). "Higher numbers of platelet-monocyte complexes were independently related to elevated levels of C-reactive protein (CRP), higher carotid-femoral pulse wave velocity, hypertension and smoking in a multivariate model." (PMID 21062475, 2010). "Patients with hypertension were significantly older (p < 0.001) and had more missing teeth (p = 0.037), as well as higher levels of VLDL (p = 0.009), triglycerides (p = 0.013), CRP (p = 0.010), and WBC (p = 0.031)." (PMID 40572711, 2025). "Although, in our study, hypertension (P=0.879), nephrotic range proteinuria (P=0.467), serum albumin levels (P=0.502), CRP (P=0.099), and reduced C3 level (P=0.453) were not considered as factors predicting RPGN." (PMID 41246678, 2025). "No meaningful interaction was observed between CRP and hypertension (p = 0.23), and stratification by ACS type (STEMI vs. NSTEMI) yielded consistent non-significant results." (PMID 41303851, 2025). "At this λ value, nine variables with nonzero coefficients were retained, including hypertension, cause of illness, NLR, SII, blood sodium, Scr, LDH, CRP, and D‐dimer." (PMID 41498031, 2025). "These SNPs have been related to several GWAS-catalog specific traits, such as AD, C-reactive protein, HDL, parental longevity, serum alanine aminotransferase, WM microstructure, cerebral amyloid deposition, hypertension and amyloid-ꞵ 42 levels (Supplementary Results)." (PMID 41561329, 2025). "Sustained stress responses over time lead to secondary alterations, elevated CRP indicating inflammation, reduced HDL-C reflecting metabolic dysfunction, and hypertension signifying cardiovascular strain, which collectively accelerate tertiary outcomes such as physical decline and disability." (PMID 41295355, 2025). "All factors that were statistically significant (i.e., p < 0.05) in the univariate analysis were included in the logistic multivariate analysis, including length of hospital stay, sex, pneumonia, hypertension, hyperlipidemia, CHD, EVD, tracheotomy, PCT, LaC, CRP, BET, Alb, BUN, and WBC." (PMID 40529435, 2025). "Periodontitis affects endothelial function through systemic inflammation involving mediators such as CRP, IL-6, and TNF-α that can affect endothelial function, which may contribute to hypertension development." (PMID 40735233, 2025). "Higher scores were significantly associated with increased all-cause mortality (per 1-point increase: HR 1.53, 95% CI 1.35–1.74, p < 0.001), independent of sex, age, HbA1c, BMI, LDL, hs-CRP, hypertension and smoking status." (PMID 40629349, 2025). "In multivariable models, insulin use and hypertension were balanced across CRP quartiles in our cohort, suggesting they did not drive the association." (PMID 41159344, 2025). "Elevated markers of inflammation, such as C-reactive protein (CRP), cytokines, and adhesion molecules, have been reported in hypertensive patients, which supports the role of inflammation in the pathogenesis of hypertension." (PMID 38396672, 2024). "These factors encompass hypertension, smoking, increased Body Mass Index (BMI), elevated hematocrit levels, high Neutrophil-to-Lymphocyte Ratio (NLR), high Platelet-to-Lymphocyte Ratio (PLR), and elevated C-reactive protein (CRP) levels." (PMID 38302950, 2024).